CTLA4 (cytotoxic T-lymphocyte associated protein 4)
Diseases named in the same sentence as CTLA4 in open-access papers (continued):
Sharing a sentence is not in itself a finding about the gene and the disease.
tumor (continued). "Additionally, higher CTLA-4 expression was more likely to be aggressive, to be of higher histological grade and advanced tumour stages, as well as advanced pathological stages." (PMID 37761948, 2023). "Immune checkpoint inhibitors (ICIs) targeting CTLA-4 and PD-1/PD-L1 to boost tumor-specific T lymphocyte immunity have opened up new avenues for the treatment of various histological types of malignancies, with the possibility of durable responses and improved survival." (PMID 37386520, 2023). "In mouse models, anti-CTLA4 antibody treatment initially resulted in the rejection of tumors, including preestablished tumors; furthermore, the rejection resulted in immunity to a secondary exposure to tumor cells." (PMID 36960057, 2023). "While the anti-tumour mechanisms of CTLA-4 antibodies are not well understood, the generally believed hypothesis is that blocking CTLA-4 causes an increased activation of proliferation of effector T-cells accompanied with a decrease in activated Treg cells." (PMID 39086690, 2023). "Most currently approved therapeutic Abs are antagonist that either directly bind to surface markers expressed on cancer cells like HER2, growth factors that support tumor growth like vascular endothelial growth factor, or regulatory proteins on cells like CTLA-4, PD-1 and PD-L1." (PMID 38006049, 2023). "Given that high EFRG expression is indicative of improved response to immune therapy, these two cell types may serve as crucial target cells mediating the anti-tumor effects of anti-PDL1/CTLA-4." (PMID 37575252, 2023). "However, cancer cells within the tumor microenvironment can escape the anti-tumor influences by stimulating these checkpoints through CTLA4 or PD-1/PD-L1 expression enhancement." (PMID 37445336, 2023). "Yet, there is increasing evidence that CTLA-4 can also be expressed by tumor cells." (PMID 37415208, 2023). "Some of these mechanisms activate the immune system to fight the tumor, while the other has a negative impact on the function of immune cells, thereby boosting tumor cell growth and metastasis, with immune checkpoints (CTLA-4/B7, PD-1/PD-L1, TIM-3, etc.)playing a pivotal role." (PMID 37419930, 2023). "However, conditional ablation of Ctla4 in adult mice was reported to confer protection from autoimmune and anti-tumor responses, suggesting the Treg-cell-intrinsic function of CTLA-4 to limit their activation and expansion." (PMID 37197667, 2023). "The anti-CTLA-4 antibody may kill tumor-specific effector Treg cells or attenuate their suppressive activity." (PMID 36839882, 2023). "In this study, using 4-ipp in combination with ipilimumab, the authors conclude that improved anti-CTLA-4 anti-tumour effect is a result of reprogramming the metabolism of metastatic melanoma by reducing hypoxia, thus improving immunogenicity and anti-tumour efficacy." (PMID 37454231, 2023). "Therefore, it is also possible that the tumors with downregulated CTLA-4 have reduced anti-tumor immunity, poor prognosis, and resistance to immunotherapy." (PMID 37197667, 2023). "Altogether, these data suggest that chemotherapy can induce an anti-tumor immune response and that neoadjuvant chemotherapy could enhance the benefits of anti-PD-1/PD-L1 and CTLA-4 immunotherapy." (PMID 37443821, 2023). "Furthermore, IFN-γ secretion, one of the most important cytokines against tumor cells, can also be affected by higher CTLA-4 expression." (PMID 36982701, 2023). "Tregs that have been activated may express PD-1, PD-L1, and CTLA-4 to suppress the activity of tumor-specific T cells." (PMID 37759229, 2023). "In addition to targeting immunogenic tumor mutations, autologous tumor-infiltrating lymphocytes (TILs) and immune checkpoint inhibitors (ICIs) could help to promote tumor growth, and antibodies that target PD-1, PD-L1, and CTLA-4 could be used as ICB drugs for the treatment of a variety of cancers." (PMID 37124611, 2023).
tumor (continued). "Besides, inhibition of casein kinase 2 (CK2) with BMS-211 substantially reduced the amount of polymorphonuclear MDSCs and macrophage differentiation, which was dramatically synergized with the anti-tumor efficacy of CTLA-4 blockades." (PMID 37386520, 2023). "In addition, CTLA-4 and PD-1 are important checkpoint pathways that maintain T-cell activation, and blocking these two pathways contributes to T-cell reactivation and tumor rejection." (PMID 38139799, 2023). "Furthermore, higher expression of both CTLA-4 at the tumor-host interface of iCCA correlates with tumor recurrence and chemo-resistance." (PMID 37138880, 2023). "Here the authors identify the ubiquitin-specific protease 5 (USP5) as a deubiquitinase for PD-1 and show that USP5 inhibition in combination with a MEK inhibitor or anti-CTLA-4 could promote anti-tumor immune responses in preclinical models." (PMID 37208329, 2023). "CTLA-4 and PD-1 had similar mechanisms in terms of tumor tolerance." (PMID 38155974, 2023). "However, on activated T cells, CTLA4 directly competes with CD28 for B7 ligands to mediate tumor immune responses." (PMID 37745297, 2023). "The hyporesponsive state of these anergic T cells may contribute to tumor immune evasion and resistance to immune checkpoint blockade such as anti-PD-1/PD-L1 and anti-CTLA-4." (PMID 36798126, 2023). "Loss of immunogenic tumor mutation associated neoantigens has also been identified as one mechanism of acquired resistance to ICIs in NSCLC patients who underwent treatment with anti-PD-1 or combined anti-PD-1 and anti-CTLA-4 ICIs." (PMID 37377970, 2023). "However, the combination therapy of CRT-NP and anti-CTLA4 ICI resulted in remarkable suppression of tumor growth rates (>70%) compared to untreated mice." (PMID 37376141, 2023). "CTLA-4, also known as CD152, is the first detected co-inhibitory checkpoint receptor (ICR) that normally expressed on T cells and is linked to the suppression of endogenous anti-tumor immunity mediated by T cells." (PMID 36109471, 2023). "As T-cell function is influenced by receptor signaling through T-cell receptors and cytokines, we hypothesized that the tumor cell secretome downregulates CTLA4 expression in human Treg cells." (PMID 37197667, 2023). "CTLA-4 expression in the MCTs was statistically higher in dogs who had non-ulcerated tumors (p = 0.019); however, no statistical differences were observed between the clinical and tumor characteristics and the immunoexpressing of this protein in the MLNs." (PMID 37370399, 2023). "Additionally, depleting CTLA-4 in Tregs affects their suppressor function and promotes tumour immunity." (PMID 37426674, 2023). "In previous studies, it has been shown that although intratumoral injection of AMPs can prime the response of tumor-specific T-cells; it is because of the presence of immune checkpoints such as PD-L1 or CTLA-4 on the tumor surface, primed specific T cells can be exhausted." (PMID 37605720, 2023). "Analyzing the subsets of these factors highly expressed by PV001-DV’s infection of PBMCs, several of the known tumor apoptosis-inducing factors such as TNF-a, IL-12p70, are observed to overcome tumor evasion mechanisms, and IL-2 is observed to be synergistic with anti-CTLA-4 therapy." (PMID 37468934, 2023). "Tumor cells evade immune destruction by activating immune checkpoint receptor proteins including cytotoxic T-lymphocyte-associated protein 4 (CTLA-4) and programmed cell death protein 1 (PD-1) found on T cells, and programmed death ligand 1 (PD-L1) found on tumor cells." (PMID 36975443, 2023). "Single-cell sequencing results showed that immune checkpoints such as programmed death-ligand 1 (PD-L1), cytotoxic T-lymphocyte-associated protein 4 (CTLA-4), and the T cell immunoglobulin and ITIM domain (TIGIT) are upregulated on the surface of tumor cells after TTFields intervention." (PMID 38067345, 2023).
tumor (continued). "Nevertheless, an effective anti-tumor immune response is thwarted by an augmented expression of immune checkpoint molecules including PD-1, its ligand anti-programmed cell death protein-ligand 1 (PD-L1), and CTLA-4 and thus immunosuppressive features of the tumor immune ecosystem." (PMID 37569431, 2023). "Interestingly, combining oral bicarbonate therapy to neutralize tumour acidity in combination with anti-CTLA-4 or anti-PD1 therapy improved antitumor responses in multiple models, including complete remissions in some subjects." (PMID 35708739, 2023). "For the CTLA-4 inhibitor ipilimumab, the three most common tissue or organ disorders were ‘neoplasms benign, malignant and unspecified’ (1,781 cases, 21.97%), ‘gastrointestinal disorders’ (1,233 cases, 15.21%) and ‘respiratory, thoracic and mediastinal disorders’ (849 cases, 10.47%)." (PMID 36600271, 2023). "Subsequent research has suggested that the anti-tumor efficacy of CTLA-4 and RANKL antibodies could be attributed to the cooperative action of T cells and NK cells." (PMID 37929901, 2023). "This suggests the possibility of a systemic activation of a functional anti-tumor response upon tbLN-directed CTLA4 blockade, hinting at a possibility of optimal ICB regimen (multi-drug and/or multi-site or multi-dosed) being potent enough to induce a complete remission." (PMID 37259163, 2023). "The vascular microenvironment may induce the expression of PD-L1 on tumor cells, CTLA-4, T-cell immunoglobulin 3 (TIM-3), and PD-1 on immunosuppressive cells, blocking the immune response." (PMID 37111629, 2023). "Therefore, the dual blockade with antiCTLA4 was tested due to the better results obtained in other neoplasms such as melanoma or renal cell carcinoma, attributed to the CTLA4 expression on regulatory T-cell surfaces." (PMID 36765821, 2023). "Thus, enhancing FcγR binding by modifying the Fc region provided a generation of engineered anti-CTLA4 antibodies with increased anti-tumor activity by Treg cells depletion." (PMID 37215135, 2023). "Significantly, researchers discovered that the combination therapy of mIDH1 inhibitor AG120 (an orally active inhibitor of mIDH1 enzyme) and anti-CTLA-4 antibody induced substantial cell death and sustained tumor-specific T-cell responses in tumor-bearing mice." (PMID 38213535, 2023). "Supplementation with anti-CTLA-4 or anti-PD-1 potentially could remedy the relative number of terminally differentiated tumor-specific CD8 T cells." (PMID 37359554, 2023). "The ICI drugs are designed to block PD1/PD-L1 or CTLA4/B7 pathway interaction, relieving the inhibitory effects on T cells, allowing re-activation, proliferation and differentiation of T cells, enhancing the immune function and anti-tumor response." (PMID 36831044, 2023). "In addition, Treg cells constitutively express CTLA4, which further plays a key role in suppressing anti-tumor immunity." (PMID 37632832, 2023). "In addition, novel ICs TIM-3 and LAG-3 are also highlighted as potential therapeutic targets to combine with PD-1 or CTLA-4 ICBs under acidic conditions to boost anti-tumour immunity." (PMID 35708739, 2023). "However, increasing evidence suggests the key role of ICOS in anti-tumor response induced by anti-CTLA4 therapy, such as ipilimumab or tremelimumab." (PMID 38127899, 2023). "As a result of the mediated CTLA4/B7 checkpoint blockage, activated T cells, including those activated by tumor antigens, can continue to proliferate, produce cytokines, and hence, perform their cytotoxic effects within the tumor microenvironment." (PMID 37111737, 2023). "OS was lower in mice irradiated at the tumour site and tumour-draining LNs compared to those only irradiated at the primary tumour, whether ICIs were directed against PD-1 or CTLA-4." (PMID 37189436, 2023).
tumor (continued). "The therapeutic mechanism of ICIs is based on targeting certain immunoregulatory signaling molecules, including cytotoxic T-lymphocyte antigen 4 (CTLA-4), programmed cell death 1 (PD-1), and its ligand 1 (PD-L1), which activate T cells and inhibit the growth of tumor cells." (PMID 37305530, 2023). "Indeed, an anti-PD-L1 or anti-CTLA-4 antibody remarkably reduced tumor volume in mice bearing Ythdf1-KO B16/F10 cells compared with an immunoglobulin G (IgG) antibody." (PMID 36650153, 2023). "Specific TRIM28 inhibitors could be further developed and validated in combination with anti-CTLA4 therapy to suppress tumor growth efficiently." (PMID 37357254, 2023). "Indeed, we found that γδT17 cells in tumor tissue are characterized by elevated expression of Treg signature genes, such as Lgals1and Ctla4." (PMID 37143122, 2023). "The overexpression of CTLA-4, PD-1, and PD-L1 can negatively regulate anti-tumor immunity." (PMID 36895477, 2023). "In addition, combining PDL1 or CTLA4 inhibition with ACT led to almost complete tumor stasis of Adam2 overexpressing and control tumors, indicating strong cooperative effects." (PMID 37258521, 2023). "Together, these results suggest that USP5 inhibition significantly enhances the efficacy of anti-CTLA-4 immunotherapy in vivo, which might be largely due to decreasing PD-1 and increasing cytotoxic activity of tumor-infiltrating CD8+ T cells." (PMID 37208329, 2023). "We hypothesized that the efficacy of IL-6 and CTLA-4 blockade may be mediated in part by tumor-derived chemokines that enhance lymphocyte trafficking into tumors." (PMID 36881480, 2023). "Furthermore, the high levels of PD-1, PD-L1, CTLA-4, LAG-3, SIGLEC15, and TIGIT were associated with poor prognosis and immunosuppression of the tumor microenvironment in ccRCC." (PMID 37175461, 2023). "FMD cycles combined with anti-PD-1/anti-CTLA4 caused a trend for an increase (statistically not significant) of both cytotoxic T cells and NK cells into tumor tissue compared to the standard diet group treated with ICIs." (PMID 37684243, 2023). "Thus, Fc-enhanced anti-CTLA4 antibodies show anti-tumor activity due to its ‘Fc-effector function’ on Treg cells." (PMID 37215135, 2023). "In addition, the combination of VEGF-blocking and TGF-β-blocking drugs was reported to exert synergistic inhibitory effects on tumor growth in B16 mice model, and these drugs significantly enhanced anti-PD-1/anti-CTLA-4 therapy and prolonged survival." (PMID 37573354, 2023). "Furthermore, MC38-tumor bearing mice showed a better response to anti-PD-1 and anti-CTLA-4 treatment after engraftment with these eleven strains." (PMID 38035338, 2023). "The combination of immune checkpoint inhibitors, specifically anti-CTLA-4 and anti-PD-1 antibodies, is now providing an effective therapeutic strategy in many cancers, including advanced melanoma, for which tumor regression and long-term durable cancer control is possible in nearly 50% of patients." (PMID 37398649, 2023). "Immunotherapies that inhibit the expression of CTLA-4 and PD-1 have been effective in the treatment of various tumors, and tumor immunotherapy requires sufficient immune cells to infiltrate the tumor microenvironment and sufficient immune checkpoint expression to achieve efficacy." (PMID 37074800, 2023). "An anti-CTLA-4 antibody may be capable of killing tumor-infiltrating effector Treg cells or lowering the suppressive activity." (PMID 36765522, 2023). "Therefore, the synergic combination of anti-CD47 with anti-PD-1 and anti-CTLA-4 induces a delay in tumor growth and improves overall survival in mice." (PMID 36829496, 2023). "In murine models, CTLA-4 blockade has been demonstrated to enhance T cell responses to cancer vaccines and tumor infiltration along with intratumoral Treg depletion, resulting in tumor control and clearance." (PMID 37180141, 2023).
tumor (continued). "Thus, anti-CTLA-4 indirectly normalizes tumor vessels by increasing pericyte coverage and vessel perfusion and decreasing vessel density in an eosinophil-dependent manner." (PMID 37587450, 2023). "When Prof. James P. Allison and his group initially introduced the anti-CTLA-4 blockade to reinvigorate anti-tumour T cells to fight solid tumours, the therapeutic effect of this breakthrough was only achieved in the context of tumours with preserved immunogenicity (hot tumours)." (PMID 37454231, 2023). "Anti-CTLA-4 antibodies may eliminate tumor-specific effector Treg cells or deplete their inhibitory activity." (PMID 36839882, 2023). "There are monoclonal antibodies such as anti-CTLA4 and anti-PD-1/PD-L1 that impair negative regulators, or checkpoints, of the adaptive immune system, leading to significant antitumor activity—and even cures—in different tumor types." (PMID 37511612, 2023). "Additionally, treatment with vorinostat along with immune checkpoint blockers, such as PD-1 and CTLA-4, can stimulate tumor apoptosis and regression in TNBC." (PMID 36810560, 2023). "Moreover, blocking the other vital TAMs receptors (e.g., CSF-1R) and inhibitory receptors (e.g., LILRB1, LILRB2, CTLA-4) by nanobodies can improve the anti-tumor immunity in the TME through reprogramming of macrophages." (PMID 36761751, 2023). "We speculate that the systematical stimulation of T cells (through anti-CTLA-4 inhibitors) is insufficient; therefore, resolving the immunosuppression of the tumor microenvironment is also needed." (PMID 37215995, 2023). "Inhibition of specific immune checkpoint proteins such as the B7:CD28 family members programmed cell death protein-1 (PD-1) and cytotoxic T-lymphocyte antigen-4 (CTLA-4) has transformed the treatment of various cancers by promoting the anti-tumor activation of immune cells." (PMID 37795437, 2023). "PD1/PD-L1 and CTLA-4 are critical immune checkpoints that play a vital role in tumor immune escape." (PMID 37805556, 2023). "After looking at the total amount of T-cells, we then investigated if we could see any activity of T-cells in the anti-PD-1 and anti-CTLA-4 treated tumor area and in the TDLN which could be an early biomarker of response." (PMID 37497236, 2023). "The immunophenotype (IPS) quantitative scoring scheme could be used to determine the determining factors of tumor immunogenicity and serve as an effective predictor for detecting anti PD-1 and anti CTLA4 antibody responses." (PMID 37872217, 2023). "Combining CD47 and PD-1/CTLA-4 blockade is another strategy that could enhance anti-tumor activity by relieving additional brakes on tumor immunity." (PMID 37958404, 2023). "Namely, high levels of blood butyrate and propionate were involved in the resistance to CTLA-4 blockade and higher frequency of Treg cells, and butyrate could impede the accumulation of tumor-specific T cells and memory T cells." (PMID 36911704, 2023). "Several preclinical models suggested that a novel orally bioavailable HDAC inhibitor HBI-8000 could augment the activity of ICIs targeting either PD-1, PD-L1, or CTLA-4, and significantly reduce tumor progression." (PMID 37386520, 2023). "The authors demonstrated on several clinically relevant BC models, including orthotopic BCs (EO771, 4T1, and MCaP0008) and spontaneous BCs (MMTV-PyVT, which mirrors BC progression in humans), that CTLA4 and PD-1 antagonists increase blood perfusion of the tumor while they exert antitumor activities." (PMID 36834641, 2023). "In addition to tumor-intrinsic mechanisms mediating response and resistance to ICI, the role of the gut microbiome as a tumor-extrinsic regulator of responses to anti-PD-1, and anti-CTLA-4, is increasingly appreciated." (PMID 36806616, 2023). "Furthermore, other immune evasion mechanisms in LGG include the upregulation of immune checkpoint molecules, such as PD-L1 and CTLA-4, within the tumor microenvironment." (PMID 37509316, 2023).